MMP2 (matrix metallopeptidase 2)
Diseases named in the same sentence as MMP2 in open-access papers (continued):
Sharing a sentence is not in itself a finding about the gene and the disease.
tumor (continued). "It has been reported that MT1-MMP is retained for a long time in melanoma tumor cells and strong fluorescent signal in tumors is due to the action of different types of MMPs, such as MMP-2 and MMP-9." (PMID 27145373, 2016). "Then, we made the tumor nodules into sections to validate MMP-2, E-cadherin, and N-cadherin expression alteration." (PMID 27995049, 2016). "Since MMP14 is an activator of MMP2 and MMP9, a possible mechanism driving tumor invasion and migration is the activation of MMP2 and MMP9 through IL-6 induced MMP14." (PMID 27613828, 2016). "MMP-2 and MMP-9 participate in proteolysis of major components of the basement membrane and are associated with tumor invasion and lymph node metastasis." (PMID 27057634, 2016). "Interaction of stromal fibroblasts and BCC tumor cells affects fibroblasts-derived MMP-2, suggesting a significant effect of this interaction in the development of cancer." (PMID 27271600, 2016). "As known, MMP2 plays a critical role in tumour progression, tumour angiogenesis and metastasis; thus a cellular scratch assay was performed for investigating the metastasis inhibition of conjugate." (PMID 27447567, 2016). "As we know, matrix metalloproteinase is necessary molecular during the tumor metastasis, particularly the MMP2 and MMP9." (PMID 26883105, 2016). "Expression of various MMPs including MMP-1, MMP-2, MMP-9, MMP-12 and MMP-14 were implicated in regulating HCC tumor progression and prognosis." (PMID 27175590, 2016). "MMP-14 and MMP-2 expression was found in most of the tumours investigated, not only in the epithelium, but in a proportion of tumours also in the stroma." (PMID 27038607, 2016). "The liberated intracellular domain (ICD) of ALK5-FL has a specific role in tumor invasion through regulation of the transcription of genes (SNAIL1, ZEB, and MMP2) involved and in association with the transcriptional regulator p300 to activate genes." (PMID 27166254, 2016). "Further support for activated invasion in tumor MES was indicated with MMP2 gene expression, which was over 8.5-fold higher for MES of IFDUC1 compared to NORMA1-4 MES." (PMID 26968831, 2016). "The functionalized AuNPs can selectively target tumor tissue with overexpressed MMP‐2, and the cleavage of the peptide linker recovers the quenched fluorescence of PpIX for cell imaging." (PMID 29313015, 2016). "In line with the activity data, only MMP2-KD tumors of U87 had a significantly reduced tumor growth rate compared to control tumors (P = 0.0053)." (PMID 26923459, 2016). "MMP2 is considered as a promising druggable target for therapy due to its important role in various processes of tumor progression like angiogenesis, invasion and metastasis." (PMID 26923459, 2016). "Their results also show that GNA12 stimulates the expression and activity of tumor promoting cytokines IL-6 and IL-8 and MMP-2 via binding and activation of NF-kB." (PMID 27551323, 2016). "Secretion of MMP2 promoted tumor cell invading through the matrigel layer which served as a reconstituted basement membrane in vitro." (PMID 27475525, 2016). "Consist with the previous researches, our data demonstrated that inhibition of REPS2 would activate RalBP1/RAC1/CDC42, increase MMP2/9, thus promote tumor invasion and metastasis." (PMID 27120794, 2016). "Collagen I as ECM component has a predominant role in tumour invasion via activating remodelling factors such as MMP2." (PMID 26287450, 2016). "This conjugate was considered to be a powerful approach for inhibiting the tumour growth and metastasis in tumor with high expression of MMP2." (PMID 27447567, 2016). "We also reported a positive correlation between the expression of MMP-2 in tumor cells and inflammation." (PMID 27429508, 2016). "The analysis of the expression of matrix metalloproteinases in a variety of tissues and selected anatomical clinical factors demonstrated a correlation between MMP-2 expression in tumor and female gender (R = 0.460, p = 0.013)." (PMID 27429508, 2016).
tumor (continued). "Several studies have shown that MMP-2 plays an important role not only in tumour invasion and metastasis, but also in cancer development." (PMID 27051552, 2016). "Tumor cells are reported to secret huge amounts of MMP2 and MMP9 in a paracrine or autocrine manner to stimulate their invasion and migration." (PMID 27034162, 2016). "The synchronous alteration of MMP2 with MTSS1 suggests that MTSS1 promotes tumor metastasis by targeting MMP2." (PMID 27230279, 2016). "Nevertheless, the cleavage of the peptide by the highly expressed extracellular MMP2 in the tumor microenvironment resulted in the exposure of cationic NPs with TAT functionalized and the enhanced intracellular penetration." (PMID 30979214, 2016). "Fibroblast-derived MMP-2 is expressed to a greater degree during the earlier stages of squamous carcinogenesis, resulting in the initiation of tumor growth." (PMID 27271600, 2016). "The matrix metalloproteinases, MMP-9 and MMP-2 function as key mediators of basement membrane degradation, angiogenesis, tumor invasion in GBM." (PMID 26940200, 2016). "Meanwhile, vitexin decreased the expression of Ki67 and MMP-2, the most commonly used markers for tumor proliferation and invasion." (PMID 27588401, 2016). "Five of these genes, CXCL12, MMP2, MMP11, VCAM1, and MME, which have previously been associated with tumor progression, angiogenesis, and metastasis, clearly discriminated between primary BC and BCBM." (PMID 27340107, 2016). "Among various MMPs, MMP-9 and MMP-2 play crucial roles in tumor cell metastasis and invasion by degradation of type IV collagen, a major component of the ECM." (PMID 26968952, 2016). "Stable knockdown of CMTM3 promotes cell migration, invasion and tumor metastasis, increases MMP2 expression and enhances MMP2 activity." (PMID 27121055, 2016). "The expression of MMP-2 was predominantly present in tumor cells and stroma (55.17% and 79.31%, resp)." (PMID 27429508, 2016). "Amino acid sequence analysis of Bs-Tx7 revealed the presence of a scissile peptide bond (i.e., Gly-Ile) for human MMP2, a potential marker of cellular tumours." (PMID 26848686, 2016). "In uterine leiomyosarcoma, MMP-2 has been found to be up-regulated and to be regarded as a key positive factor of tumor invasion and metastasis." (PMID 27907907, 2016). "In our study, we noted a positive expression of MMP-2 in 55.17% of tumor cells and in 79.31% of the stroma, which was significantly higher than in the normal pancreas (3.45%)." (PMID 27429508, 2016). "Fe-MIL-101 has the potential to inhibit tumour and endothelial cell growth and migration mainly through downregulation of MMP-2/9 protein expression." (PMID 27188337, 2016). "More importantly, Bit1 downregulation significantly lowered Bcl-2 and MMP-2 levels in EC9706 xenografted tumor tissues, meanwhile triggered apoptosis after treatment with different doses of Bit1 shRNA." (PMID 26956728, 2016). "NDRG2 antagonizes TGFβ1-mediated tumor cell invasion by down-regulating the expression of matrix metalloproteinase 2 (MMP2) and laminin 332 pathways, with concomitant suppression of Rho GTPase activity." (PMID 26506239, 2016). "The specificity of conjugate in HT-1080 and U87MG tumor cells was derived from various expression levels of MMP2 in cells." (PMID 27447567, 2016). "Immunohistological staining showed that expression of Ki-67 and MMP-2, which are regarded as indices evaluating proliferation and invasion of tumor, were decreased in the vitexin treatment group." (PMID 27588401, 2016). "To understand the potential mechanisms of Pol ι-mediated tumor invasion and metastasis, we examined the effect of altered Pol ι levels on MMP-2 and MMP-9 expression in our model systems." (PMID 27057634, 2016). "Recently, IL-6 has been found to promote tumor invasion and angiogenesis, in addition to proliferation and survival, but through upregulation or activation of MMP2 and MMP9." (PMID 27613828, 2016).
tumor (continued). "Our finding suggested that the hexapeptide PVGLIG is capable to act as a controlled and sustained drug carrier of paclitaxel for the treatment against tumour proliferation and metastasis with high MMP2 expression." (PMID 27447567, 2016). "At the base of the invadopodia of the tumour cell, the activation of MMP-2 by MMP-14 takes place, so the observed correlation between MMP-14 and MMP-2 that has been found in other studies, is confirmed in our study." (PMID 27038607, 2016). "BSG (CD147, EMMPRIN) is an inducer of tumor cell associated MMPs, including MMP1, MMP2, MMP3, and MMP9." (PMID 26769849, 2016). "Strong implication of MMP-2 is found in angiogenesis and promotes tumor metastatic potential playing crucial role not only in invasion but also in determination of cancer cell transformation, growth, apoptosis, and signal transduction pathways." (PMID 26880913, 2016). "During this tumor invasion and metastasis, several matrix metalloproteinases (MMPs) like MMP-2 and MMP-9 play a critical role by degrading the extracellular matrix and components of the basement membrane." (PMID 27659937, 2016). "In animals, MMP2 inhibitors prevented tumor dissemination and the formation of metastases by anti-angiogenic properties." (PMID 27447567, 2016). "Among them, MMP-2 (gelatinase-A) and MMP-9 (gelatinase-B) are mostly associated with tumor migration, invasion and metastasis in various cancers." (PMID 27074554, 2016). "Amino acid sequence analysis of Bs-Tx7 revealed the presence of a scissile peptide bond (i.e., Gly-Ile) for human MMP2, whose activity is increased in the case of tumour malignancy." (PMID 26848686, 2016). "Previous results demonstrated that MSC-derived exosomes can modulate the function of tumor cells by induction of MMP-2 and ecto-5’-nucleotidase activity resulting in a more complex tumor microenvironment with higher tumor heterogeneity." (PMID 27608835, 2016). "MMP-2 and MMP-9 are the two most important proteins associated with tumour cell invasion and metastasis." (PMID 26880967, 2016). "Matrix metalloproteinase-2 (MMP-2), called as 72 kDa type IV collagenase and gelatinase A, can promote the tumor invasion and metastasis by degrading type IV collagen wihcih is the most abundant component of the basement membrane." (PMID 27907907, 2016). "Particularly, abnormal expression of MMP2 and MMP9 is often detected in solider tumor tissues and is associated with tumor metastasis in many cancers including HCC." (PMID 26730736, 2016). "A close sequence and structural comparison revealed the presence of a scissile peptide bond (i.e., Gly-Ile) for human MMP2, whose activity is increased in the case of tumour malignancy." (PMID 26848686, 2016). "In the tumor microenvironment, the overexpressing MMP2 and reduced pH were commonly combined used to improve the tumor targeting and cellular internalization." (PMID 27791203, 2016). "Of particular importance is the activation of XTEN-Killin by MMP-2 expressing tumor or tumor stromal cells." (PMID 27295081, 2016). "Tumor metastasis model in vivo showed much more metastatic nodules of lung in the Dicer knockdown group than the control group via increased MMP-2 expression." (PMID 27732931, 2016). "A strong positive correlation was noted between MMP-2 in tumor tissue and the presence of stronger inflammation (R = 0.690, p = 0.0001)." (PMID 27429508, 2016). "Similar to MMP-2, the collagenases MMP-1 and MMP-13 are expressed in stromal cells, particularly in tumor-associated fibroblasts." (PMID 27271600, 2016). "IHC staining showed higher TR4 level, more macrophage infiltration, lower TIMP-1 and stronger MMP2/MMP9 in tumor tissues of the Gleason score 5 + 4 patients compared with the Gleason score 3 + 3 patients." (PMID 25623427, 2015). "In another study, Fukumura designed a QDs-GNP with shrinkable size triggered by MMP-2, thus releasing small-sized QDs for deep tumor penetration." (PMID 26517810, 2015).
tumor (continued). "In vitro and in vivo research has shown that MMP2 over-expression is necessary for tumor invasion and that MMP2 and MMP9 promote tumoral cell colony formation." (PMID 26082904, 2015). "The important role of MMP2 in tumor neovascularization, cell infiltration and metastasis formation as a tumor-enhancing gene has been well-established." (PMID 25872784, 2015). "The expression of MT1-MMP and the activation of MMP-2, for instance, strongly correlate with tumor growth, neovascularization, and metastasis." (PMID 25855056, 2015). "The results confirmed that Angio-DOX-DGL-GNP possessed better penetration ability after incubation with MMP-2 and the reduction of particle size was beneficial for enhancing penetrating efficiency through the tumor spheroids experiments." (PMID 26517810, 2015). "Subsequent functional analyses revealed that only miR-29b attenuates cell migration and MMP-2 activity; thus, we used an miR-29b mimic to investigate functions of miR-29b as tumor suppressor in GBM cells." (PMID 26155940, 2015). "MMP2 activity has also been reported to be effectively reduced by anti-cancer agents that target tumor vessel formation." (PMID 25887757, 2015). "MMP-2, -7, and -9 are thought to be important in tumor metastasis and tissue remodeling; therefore, the present study investigated the gene expression of MMP-2, -7, and -9 during the treatment of Hep3B cells with trigonelline for 24 h." (PMID 26699938, 2015). "Extracellular matrix promotes the migration and invasion of tumor cells through the production of matrix metalloproteinase (MMP)-2 and -9." (PMID 26404213, 2015). "The impact of BASIGIN on MMPs production by tumour cell lines was first evaluated by analysing the MMP2 and MMP9 activities in CM from wt versus BSG−/− tumour cell lines alone, or co-cultured with fibroblasts." (PMID 26284589, 2015). "A previous study verified that MMP-2 affects the immune response and extracellular matrix remodeling, promotes formation of tumor angiogenesis and contributes to tumor metastasis." (PMID 26005051, 2015). "The aim of the study was to demonstrate the immunohistochemical expression of proteins that affect the metastatic potential of a tumour, including matrix metalloproteinase 2 (MMP-2) and E-cadherin." (PMID 27486511, 2015). "Previous studies has shown that binding of SDF-1α to CXCR4 plays a role in tumour metastasis by increasing invasion associated with MMP-9 and MMP-2 activation 20,27,28." (PMID 25753200, 2015). "Zymogel analysis of MMP2 and MMP9 gelatinase activity showed that, while MMP9 is weakly expressed in all cells tested, MMP2 expression in extracellular medium varies between tumour cell lines." (PMID 26284589, 2015). "MMP2 and MMP9 expression was statistically associated with a number of tumor features such as location (P=0.002), tumoral differentiation, tumoral stage and tumoral relapse." (PMID 26082904, 2015). "IL8 upregulates MMP-2 in tumor cells, which is thought to be responsible for its angiogenic activity." (PMID 26742965, 2015). "Among these MMPs, the activity of two gelatinases, MMP-2 and MMP-9, was found to be particularly associated with tumor metastasis." (PMID 25625511, 2015). "Among various MMP types, MMP-2 play pivotal roles in tumor cell invasion and metastasis by degradation of type IV collagen, the major component of the cartilage." (PMID 25404641, 2015). "More importantly, the degradation of the GNP core by MMP-2 facilitated the release of small-sized Angio-DOX-DGL-PEG at tumor sites, which can largely decrease the diffusional hinderance." (PMID 26517810, 2015). "As a well-known oncogene in cancer, MMP2 promotes tumor invasion and metastasis by digesting the extracellular matrix surrounding the malignant tissue." (PMID 25784655, 2015).
tumor (continued). "There are many cytokines secreted by aHSCs that are associated with tumor invasion and metastasis, including HGF, EGF, IL-1, IL-2, IL-6, MMP-2, MMP-9, TGF-β, TNF-α, VEGF and members of the Wnt signaling family." (PMID 26517671, 2015). "Several genes showed progressive increases during tumor growth, including Mmp2, Mmp3, Mmp13 and Mmp16, whereas Timp2 and Mmp27 showed more dynamic fluctuations in expression." (PMID 25848906, 2015). "We also confirmed positive associations between CEBPD amplification and overexpression and MMP2 expression in UC tumor samples." (PMID 26307680, 2015). "As a MMP superfamily member, MMP2 specifically degrades type IV collagen, a major component of the extracellular matrix and basal lamina, and is a major factor in tumor invasion and angiogenesis." (PMID 26063204, 2015). "Of the MMPs, MMP-2 is important in tumor invasion and metastasis due to the ability of MMP-2 to specifically degrade collagen IV." (PMID 26005051, 2015). "The expression of Mmp2, -3, -9, -13 was quantified by qRT-PCR using RNA isolated from microdissected tumor cells." (PMID 26193700, 2015). "More importantly, the penetration ability of Angio-DOX-DGL-GNP after incubation with MMP-2 was dominantly enhanced in tumor spheroids." (PMID 26517810, 2015). "Tumoral grade, tumoral stage, lymphatic metastasis and history of smoking were significantly related to MMP2 and MMP9 expression." (PMID 26082904, 2015). "Src-FAK signaling has been recently reported to promote E-cadherin internalization, which facilitates tumor cell motility, inhibits the endocytic pathway, and activates MMP2 and MMP9 during cancer progression." (PMID 25969668, 2015). "The presence of ATF3 and MMP2 proteins was mainly manifested as brown particles in the tumor cytoplasm and marginally in the nuclei." (PMID 25872784, 2015). "Several genes that are implicated in angiogenesis (Vegfa, Hgf), suppression of immunity (Arg1, Tgfb3), and tumor invasion (Mmp2, Mmp14, Ctgf) were also highly expressed in our GAMs data set." (PMID 25658639, 2015). "A conjugate of melittin/avidin engineered to target cancer cells with high matrix metalloproteinase 2 (MMP2) activities lead to a significant decrease in the size of B16 tumor in mice." (PMID 25657649, 2015). "Our results indicated that resistin induced up-regulation of MMP-2 expression and tumor metastasis by down-regulation of miR-519d through the AMPK/p38 pathway." (PMID 25404641, 2015). "Matrix metalloproteinase 2 (MMP2) aids tumor cell migration by digesting the extracellular matrix surrounding the tumor cells." (PMID 26329521, 2015). "MMP-2 and MMP-9 are the key members of the MMP family, and they are closely associated with tumor metastasis since they can degrade the extracellular matrix and disrupt the basement membrane." (PMID 25452809, 2015). "Quantitation of transcript levels in cultured tumor cells demonstrated that isoproterenol upregulated MMP2 and MMP9 expression by two-fold and four-fold, respectively, with the endogenous catecholamine norepinephrine shown to have similar effects." (PMID 26193320, 2015). "Previous reports have showed that MMP–2, Bcl–2 and Mcl–1 are direct targets of miR-29a in regulating tumor progression in different cancer cells." (PMID 26441331, 2015). "To further confirm the relationship by which PP4C promote tumor growth and metastasis via upregulation of MMP-2 and MMP-9, we evaluated the expression levels of PP4C, MMP-2 and MMP-9 in vivo." (PMID 25927939, 2015). "As MMP2 and MMP9 are usually associated with tumour progression in a BSG-dependent way, we investigated their expression in a series of BASIGIN-positive human tumour cells." (PMID 26284589, 2015). "To demonstrate the association between EFEMP1-mediated tumor cell invasion and MMP-2, we showed that MMP-2 protein and mRNA levels increased in 143B and U2OS cells stably transfected with EFEMP1 expression plasmid compared with the empty vector control groups." (PMID 25987128, 2015).